MEN1 (menin 1)
Diseases named in the same sentence as MEN1 in open-access papers (continued):
Sharing a sentence is not in itself a finding about the gene and the disease.
tumor (continued). "Thus, similar to PanNETs, the tumor suppressing pathways involving PHLDA3 and MEN1 are distinct in rectal NETs, and their development involves the functional loss of both pathways." (PMID 32521808, 2020). "Expression of insulin-like growth factor II (IGF II), with a 2.5-fold increase in MEN1-depleted BON1 cells in comparison to unedited BON1 cells, is an important early genetic and epigenetic event in the development of many tumor types, including mouse P-NETs36–39." (PMID 32884006, 2020). "Alpha-like PanNETs were enriched for tumours with only MEN1 mutations (11/19), 8/19 α-like PanNETs were MEN1/DAXX/ATRX wild-type and none harboured MEN1 and DAXX/ATRX mutations." (PMID 33288854, 2020). "We confirmed the presence of two driver genes, MEN1 and DAXX, mutations in which were found in one-fifth of PNET samples but not in other tumor types." (PMID 32586046, 2020). "We have previously established a conventional mouse knockout model of MEN1 on a mixed 129S6/SvEv and C57BL/6 background, whereby Men1+/- mice develop tumours of the parathyroids, pancreatic islets, anterior pituitary, adrenal cortex and testes or ovaries by the age of 12 months." (PMID 32348957, 2020). "Consistent with the human MEN1 syndrome, MPR mice recapitulated a gender bias in tumor development." (PMID 31160716, 2020). "Further study is needed to resolve this controversy regarding the prognostic value of chromatin remodeling alterations including MEN1, DAXX, and ATRX, which may be tumor stage and grade-specific." (PMID 31692857, 2019). "Multiple endocrine neoplasia 1 (MEN1) patients (n = 7) more commonly had a G1 (71%) rather than a G2 (29%) tumor and none had a G3 tumor, but the difference was not statistically significant (P = 0.470)." (PMID 31872324, 2019). "One MEN1 patient with 68Ga-DOTANOC-positive and 18F-FDG-negative primary tumor underwent distal pancreatectomy and splenectomy and histological analysis revealed a G2 T2N1M1 tumor." (PMID 31872324, 2019). "PDCD4, located at 11q13 close to MEN1, has been found to be absent in NETs and has been shown to act as a tumor suppressor in neuroendocrine cells." (PMID 28903345, 2017). "We did not observe any correlation between PTEN, MEN1 and DAXX/ATRX alterations (not shown), neither between DAXX/ATRX loss and the initial grade of the tumor (p=0.093)." (PMID 28454119, 2017). "Men1+/−/Cdk4−/− mice have been demonstrated to not develop any tumours, whereas Men1+/−/Cdk2−/− mice develop pituitary and pancreatic tumours comparable to those in Men1+/− only mice." (PMID 26320859, 2016). "As Men1 is ubiquitously expressed, the basis for the highly tissue-restricted tumor distribution in MEN1 is not understood." (PMID 26709830, 2015). "This is consistent with the literature in adult patients, which reports larger tumours and a more aggressive presentation in patients with MEN1 versus without MEN1 (85% vs. 42%; p < 0.001)." (PMID 22024364, 2011). "The downregulation of CDKN1B found in prostate lesions in Men1 mutant mice suggests the in vivo importance of CDKN1B inactivation in the tumorigenesis related to Men1 inactivation, similar to observations in other mouse Men1 tumour models." (PMID 20663219, 2010). "Moreover, MEN1 increases the stability of the transcription factor FOXO1, which might promote or repress tumor growth in a dose-dependent manner." (PMID 38003662, 2023).
tumor (continued). "In addition, nucleophosmin (NPM1m) and meningioma-1 mutations (MN1mut) confer dependency on MEN1 and sensitivity to inhibitors of MEN1–KMT2A interaction despite the non-rearranged KMT2A in these neoplasms." (PMID 38003662, 2023). "As for this group, the PPV was 100% and loss of menin immunohistochemistry could be—in conjunction with other indications—an extra reason to suggest earlier genetic counseling and not wait for a second MEN1-related tumor type to occur." (PMID 37199453, 2023). "Menin depletion inhibited proliferation of all cell lines, except for the primary tumour-derived Caov-3 cells, confirming results obtained by CRISPR-Cas9 screening according to which loss of MEN1 expression does not exert significant impact on Caov-3 cell proliferation." (PMID 36333801, 2022). "We then extended our expression analysis to MEN1 mRNA expression in a pooled series of 2081 clinical tissue samples publicly available, including 272 “normal” samples (normal tissue and benign prostate hyperplasia: BPH), 1643 PC primary tumor samples, and 90 PC metastatic samples." (PMID 34711954, 2022). "Interestingly, LOH at the PHLDA3 and MEN1 loci were not mutually exclusive, as would be expected if PHLDA3 and MEN1 were on the same tumor-suppressing pathway." (PMID 32521808, 2020). "However, the influence of genetic background and potential role of genetic modifiers on the development of tumours in adult Men1+/- mice have not been previously studied." (PMID 32348957, 2020). "However, in contrast to its critical role in other cancers, elimination of ARC in the setting of Men1 inactivation does not reduce β-cell tumor burden." (PMID 26709830, 2015). "We hypothesized that this regulatory network could mimic and substitute the second somatic “hit” of tumor suppressor inactivation in tissues in which MEN1 LOH has not yet occurred or could represent an intermediate step before the MEN1 LOH." (PMID 22761894, 2012). "All nine patients presenting with a constitutional gene mutation (e.g., MEN1 and NF1) were alieved at the 10 year follow-up period, showing a good outcome, while the OS was not different (p = 0.75) in 19 patients with concomitant neoplasia as compared to 52 without." (PMID 39001434, 2024). "The pathway leading to MEN1 tumor development and progression could be explained by the proposed negative feedback loop between menin and miR-24-1 acting as a “homeostatic regulatory network” that needs to be “broken” to induce the somatic LOH “hit” and, consequently, the progression to neoplasia." (PMID 34298972, 2021). "Authors hypothesized that this regulatory network could mimic and substitute the second somatic “hit” of tumor suppressor inactivation in tissues in which MEN1 LOH has not yet occurred, probably representing an intermediate step before the irreversible genetic MEN1 LOH." (PMID 34298972, 2021). "The absence of MEN1 mutations reported for yolk sac and mature teratoma testis tumor (the tumor described in this report), within the ATLAS genome and COSMIC databases may well be due to the rarity of this tumor histotype." (PMID 31249555, 2019). "The tumor cells were positive for Sftpc but negative for CC10 and menin, suggesting that the tumors indeed arose from specific Men1-deleted ATII cells." (PMID 32081882, 2020). "In MEN1-negative patients, PHPT, PA, and GEP-NET was the earliest tumor in 49.4, 27.3 and 13.0% of cases, respectively." (PMID 31044390, 2019).
cancer (123 papers, 2006 to 2026). A tumor composed of atypical neoplastic, often pleomorphic cells that invade other tissues. "Still, a pan-cancer study reported that several mutations disabling MEN1 are somatic and that only a small fraction of germline mutation have the potential to be pathogenic and drive oncogenesis." (PMID 38891107, 2024). "Investigating these molecular interactions offers promising avenues for understanding the underlying mechanisms and identifying novel therapeutic targets in MEN1-associated cancers." (PMID 38279330, 2024). "The anti-proliferative function of MEN1 is reported in normal mammary epithelium cells and females with MEN1 syndrome are at high risk of developing cancer." (PMID 37437063, 2023). "The cancer driver screening also highlighted general differences in the attractor landscapes when investigating WT and MEN1 loss conditions." (PMID 37270586, 2023). "Model-based simulations suggested drivers of cancer progression as both first and second hits after MEN1 loss." (PMID 37270586, 2023). "We selected MEN1 gene mutations from a compiled list of 253 missense mutations observed in various human cancers." (PMID 35941657, 2022). "MEN1 variants were previously associated with LTL in controls from the PLCO Cancer Screening Trial and the Nurses’ Health Study." (PMID 36221106, 2022). "IHC analysis showed menin loss in both adenoma and carcinoma from Men1+/ΔN3-8 and hTS/Men1+/ΔN3-8 mice, respectively, whereas intact menin expression was observed in normal islets." (PMID 36048542, 2022). "Multiple neuroendocrine neoplasia type 1 (MEN1) is a rare genetic disorder with an autosomal dominant inheritance, predisposing carriers to benign and malignant tumors." (PMID 33807230, 2021). "Its management is challenging, as MEN1 affects different endocrine tissues and predisposes to both benign and malignant tumors." (PMID 34889280, 2021). "Inherited MEN1 mutations are associated with certain parathyroid and pancreatic syndromes while spontaneous mutations have been detected in cancer cells." (PMID 32937789, 2020). "Somatic mutations in MEN1, a gene identified as a familial cancer risk gene and as an inducer of genome wide hypermethylation, were identified as putative drivers." (PMID 32384699, 2020). "Other cancers that have been anecdotally described in association with MEN1 include hepatocellular carcinoma, melanoma, lung adenocarcinoma, renal cell carcinoma, papillary thyroid cancer, and prostate cancer." (PMID 33312161, 2020). "Multifocal pNETs occur in more than 75% to 90% on a MEN1 background, with pNETs representing one of the most frequent cancer-related causes of mortality in MEN1 patients." (PMID 32947997, 2020). "Notable somatic alterations included a MEN1 driver, several epigenetic modifiers, and therapy-induced mutations that impacted multiple other cancer-relevant pathways and altered the neoantigen landscape." (PMID 29440180, 2018). "The primary tumor sample contained only one overtly cancer-related gene mutation, an expressed frameshift insertion in MEN1 (K237fs)." (PMID 29440180, 2018). "In this study, we investigated the possible association of MEN1 malignant tumours with CDKN1B V109G polymorphism." (PMID 25824098, 2015). "One known cancer-associated gene, the tumour suppressor gene MEN1, was located in the highly recurrently lost regions." (PMID 25955013, 2015). "The final goal is to offer patients with MEN1 germline mutations an optimal cancer prevention and treatment program." (PMID 17014705, 2006).
cancer (continued). "Notably, several genes identified in our CRISPR screen, including ARID1A, PSIP1, RNF2, UBE2D and MEN1, were previously associated with chemoresistance in various cancer types, reinforcing the biological relevance of our findings." (PMID 40583060, 2025). "Notably, the mutation detected in the subject was located in exon 9 of the MEN1 gene, and one study showed that mutations in exon 2, 9, and 10 of the MEN1 gene are associated with a higher incidence of malignant tumors." (PMID 40421248, 2025). "The MEN1 gene, encoding the menin protein, plays a regulatory role in several cancers." (PMID 40837414, 2025). "Additionally, the mean Cancer Cell Fractions (CCF) of MEN1/DAXX variants were significantly higher when compared to other genes (Mean CCF: 96.32% in MEN1/DAXX vs. 80.27% in others)." (PMID 38448900, 2024). "Finally, all individuals in whom a MEN1 germline mutation has been detected should be screened indefinitely through adult life for the development of MEN1-associated cancers." (PMID 38294658, 2024). "PC is a rare cancer, often involving sporadic cases with somatic mutations in genes including MEN1." (PMID 39056047, 2024). "MEN1 mutation represents the most frequent alteration in pancreatic neuroendocrine malignancies." (PMID 34878630, 2022). "This is consistent with the hypothesis that the development of MEN1-associated cancers occurs in two stages, where MEN1′s first allele is affected by the germline mutation, and a second somatic inactivation of the unaffected allele (LOH)." (PMID 36139607, 2022). "The selected MEN1 mutants are associated with different human endocrine or cancer pathologies." (PMID 35941657, 2022). "In addition, in recent years exome and whole genome sequencing studies have revealed MEN1 gene mutations in many types of cancer, such as adrenocortical, uterine, breast and other cancers." (PMID 35941657, 2022). "However, though the growth of DP-NETs tends to be slow, these tumors are the primary cause of MEN1-cancer-related deaths." (PMID 33649917, 2021). "DP-NETs are the primary cause of MEN1-cancer-related deaths." (PMID 33649917, 2021). "We have identified a hotspot mutation in MEN1 that effects 4% of BRAF mutant cancers." (PMID 32384699, 2020). "Interestingly, especially in the context of highly methylated BRAF mutant cancers, the loss of MEN1 has been associated with aberrant DNMT1 activity and an altered DNA methylation landscape." (PMID 32384699, 2020). "However, as this is a pan cancer analysis it suggests that, if MEN1 germline mutations significantly contributed to cancer phenotypes, they would be detectable in various patient samples." (PMID 32937789, 2020). "The goal of this study was to investigate whether MEN1 germline mutations appear in cancer cells, which would suggest that they predispose patients to cancer." (PMID 32937789, 2020). "We also report an instance where a pathogenic variant in the established cancer gene MEN1 (c.778G > A) is present in an affected family member, but absent from an affected second-degree relative, implying possible differential genetic causality for disease within a single pedigree." (PMID 31681433, 2019). "In particular, ACs had frequencies of MEN1 losses and mutations comparable to those in TCs, and their overall mutational burden was 2.6 times higher than that in TCs and 2.9 times lower than that in carcinomas." (PMID 27873319, 2017). "Consequently, PanNETs with MEN1/DAXXwild mutations may potentially follow an alternative cancer development pathway." (PMID 38448900, 2024). "However, our results may indicate that a decrease in MEN1 expression levels may result in increased susceptibility to DNA damage and a predisposition to cancer." (PMID 35807169, 2022). "A direct role of miRNA dysregulation in human cancers, including MEN1 tumorigenesis, has been reported." (PMID 40507887, 2025).
cancer (continued). "The MEN1 gene or menin protein was significantly reduced in MEN1-KD T24, 5637, and HT-1197 cells compared with siCtrl-treated cancer cells at 72 h post-transfection." (PMID 40837414, 2025). "As outlined in Section 3, it is evident that the epigenetic regulation of PNETs remains an insufficiently explored domain in comparison to other extensively researched cancers, barring a few exceptions like the MEN1 and SSTR2 signaling pathways." (PMID 38279330, 2024). "These examples underscore the intricate interplay between ncRNAs and the MEN1 pathway, highlighting the diverse regulatory roles of ncRNAs in shaping the landscape of cancer progression." (PMID 38279330, 2024). "Motivated by this possibility, we divided the 10 patients into two groups (MEN1/DAXXmut and MEN1/DAXXwild) and explored differences between these groups in relation to cancer formation." (PMID 38448900, 2024). "NcRNAs exert nuanced control over gene expression, contributing to the dynamic modulation of the MEN1 pathway in cancer progression." (PMID 38279330, 2024). "MEN1 even plays a role as a tumor suppressor gene in CRC, with recent work finding a hotspot mutation in MEN1 that affects 4% of BRAF mutant cancers." (PMID 38279330, 2024). "These encouraging preclinical results warrant future studies to design strategies of rationally repurposing and/or combining PRC2 and MEN1 inhibitors for synergistic anti-cancer effects." (PMID 37460547, 2023). "Nonsynonymous mutations were also identified in 51 additional cancer genes in single primary ileal NETs and metastases, including ALK, DAXX, KRAS, and MEN1." (PMID 35922826, 2022). "Genetic variants of unclear significance were however detected in genes such as CDH1, DICER1, MEN1, RET, CREBBP, RAD51C, or SOS1, which are linked to autosomal dominant predisposition to cancer." (PMID 35250968, 2022). "In contrast, LOH in hTS/Men1+/ΔN3-8 mice resulted in carcinoma with high penetrance in the pancreas, expressing high levels of ectopic hTS." (PMID 36048542, 2022). "In summary, we observed that TS overexpression accelerated carcinoma onset as early as 5 months of age, demonstrating an onset of carcinoma 3 months earlier in hTS/Men1–/– as compared with Men1–/– mice." (PMID 36048542, 2022). "Pancreatic adenoma and carcinoma tissues isolated from Men1–/– (n = 4) and hTS/Men1–/– mice (n = 5) were subjected to immunostaining with anti–Ki-67." (PMID 36048542, 2022). "At 8–10 months of age, 53.3% of hTS/Men1–/– mice developed carcinomas whereas only 26.7% of Men1–/– mice had carcinomas (n = 15, P < 0.05)." (PMID 36048542, 2022). "We also observed that 9 of 16 hTS/Men1–/– mice (56.3%) and 5 of 16 Men1–/– mice (31.3%) developed carcinoma at 8 months of age." (PMID 36048542, 2022). "At >10 months of age, hTS/Men1–/– mice (n = 18) still showed a higher frequency of carcinomas as compared with Men1–/– mice (n = 32) (88.9% vs. 68.8%, P < 0.05), but the difference was less prominent than at the earlier time periods." (PMID 36048542, 2022). "Before 8 months of age, 21.7% of hTS/Men1–/– (n = 23) mice had carcinomas as compared with 0% carcinoma in Men1–/– mice (n = 20) (P < 0.05)." (PMID 36048542, 2022). "Subsequent analysis revealed that MEN1 alterations are also found in a subset of pancreatic endocrine tumors and pituitary adenomas, as well as several other cancers." (PMID 32937789, 2020). "Although a TCGA analysis identified MEN1 and PRKAR1A as putative cancer genes in ACC, the low frequency of mutations—4.7% and 2.3% for MEN1 and PRKAR1A, respectively—render their importance in this disease at best marginal." (PMID 33148256, 2020). "The TCGA-identified putative cancer genes MEN1 and PRKAR1A were found in low frequency—4.7 and 2.3%, respectively." (PMID 33148256, 2020). "After clinical and genetic diagnosis as MEN1, the patient underwent left inferior and right superior parathyroidectomy—the pathology being carcinoma." (PMID 33101196, 2020).